PTH (parathyroid hormone)
Diseases named in the same sentence as PTH in open-access papers (continued):
Sharing a sentence is not in itself a finding about the gene and the disease.
secondary hyperparathyroidism (continued). "When treating VitD deficiency in association with secondary hyperparathyroidism, documentation of a decrease in PTH confirms that homeostatic mechanisms had been triggered prior to VitD3 supplementation." (PMID 38947416, 2024). "The increased risk is likely due to CKD-associated or secondary hyperparathyroidism, as seen in this case, which places greater dependence on PTH-mediated bone resorption for the maintenance of serum calcium." (PMID 39664123, 2024). "The main diagnostic dilemma in normocalcemic hyperparathyroidism is differentiating this condition from secondary hyperparathyroidism and other causes of elevated parathyroid hormone (PTH) levels in eucalcemic patients, including potential assay interferences." (PMID 39529983, 2024). "This suggests that a very low 25(OH)D level is required to activate the PTH axis, leading to secondary hyperparathyroidism and bone loss." (PMID 38032745, 2024). "It will be of interest if the expression of the PTH result as multiples of the age-related assays specific reference interval improve the utility of individual result in secondary hyperparathyroidism associated with chronic kidney disease." (PMID 38292595, 2024). "Several studies found that the ApaI "aa" genotype was associated with higher PTH levels, increased bone turnover markers (such as intact osteocalcin), and a higher risk of secondary hyperparathyroidism in ESRD and hemodialysis patients." (PMID 39156357, 2024). "This provides a rationale to incorporate 24,25(OH)2D measurement in assessing VitD status—especially, to differentiate patients with secondary hyperparathyroidism from patients with subclinical VitD deficiency but normal PTH levels." (PMID 38947416, 2024). "This study was performed to investigate the incidence and diagnostic rate of CKDin hospital as well as PTH testing and treatment for secondary hyperparathyroidism (SHPT) in patients with stage 3 to 5 CKD." (PMID 37739989, 2023). "Typically, CKD causes secondary hyperparathyroidism with increased fibroblast growth factor 23, parathyroid hormone (PTH), and serum phosphorus (P), which affects bone metabolism." (PMID 36574105, 2023). "VD and calcium supplementation at low doses is also used in the treatment of primary and secondary hyperparathyroidism, to restore plasma levels and prevent the deficiency of both molecules in patients with abnormal PTH production or renal insufficiency." (PMID 38117357, 2023). "The most important predictive risk factors for the post-transplant development of secondary hyperparathyroidism are blood calcium, alkaline phosphatase, and PTH levels at the time of transplantation, type of dialysis, and graft function." (PMID 37069889, 2023). "Secondary hyperparathyroidism (SHPT) is a disease caused by an increase in parathyroid hormone (PTH), excessive parathyroid gland hyperplasia, and abnormality in calcium and phosphorus balances in bone mineral metabolism." (PMID 35624577, 2022). "A hallmark of CKD-MBD is secondary hyperparathyroidism with increased parathyroid hormone (PTH) synthesis and release and reduced expression of calcium-sensing receptors on the surface of parathyroid cells and eventually hyperplasia of parathyroid gland cells." (PMID 37674998, 2022). "First, the high PTH does point to a degree of secondary hyperparathyroidism as a result of increased bone turnover associated with 25(OH)D deficiency." (PMID 35505326, 2022). "PTH is high in individuals with 25(OH)D deficiency, characterizing secondary hyperparathyroidism, which is associated with the reduction in neuromuscular strength." (PMID 36109388, 2022). "In calcium deficiency rickets, patients present with secondary hyperparathyroidism as the low calcium levels stimulate the increased production of PTH." (PMID 35626880, 2022). "Secondary hyperparathyroidism (SHPT) is caused by excessive PTH production and release, as well as parathyroid enlargement." (PMID 36267284, 2022).
secondary hyperparathyroidism (continued). "Day 1 PTH < 10 pg/mL is an effective determinant; however, in vitamin D-deficient patients who have secondary hyperparathyroidism, postoperative PTH can be an unreliable predictor." (PMID 33498810, 2021). "Secondary hyperparathyroidism (SHPT) is defined as (appropriately) increased PTH secretion due to an underlying stimulus." (PMID 34371838, 2021). "Recent experimental data identified parathyroid hormone (PTH) as a driver of adipose tissue browning and wasting, but little is known about the relations among secondary hyperparathyroidism, weight loss, and risk of mortality in dialysis patients." (PMID 34060245, 2021). "Many diseases with elevated PTH, such as primary hyperparathyroidism and chronic kidney disease with secondary hyperparathyroidism, are associated not only with mineral bone disease but also an increased risk of impaired cognitive function and AD." (PMID 34959925, 2021). "When renal function is impaired, an increase in phosphate will cause the secretion of PTH but reduce the active form of vitamin D, which will induce secondary hyperparathyroidism." (PMID 34955791, 2021). "Several studies have associated increased PTH concentrations with adverse health outcomes, particularly musculoskeletal issues, since secondary hyperparathyroidism is associated with increased bone turnover rates and consequently increased bone loss." (PMID 32231092, 2020). "Elevated parathyroid hormone (PTH) levels in secondary hyperparathyroidism (SHPT) lead to vascular calcification, which is associated with cardiovascular events and mortality." (PMID 32343734, 2020). "We investigated the association between changing patterns of phosphorus, calcium and intact parathyroid hormone levels and all-cause mortality in hemodialysis patients with secondary hyperparathyroidism." (PMID 33045994, 2020). "Normocalcemic hyperparathyroidism (NPHPT) is characterized by persistently normal calcium levels and elevated parathyroid hormone (PTH) values, after excluding other causes of secondary hyperparathyroidism." (PMID 32072184, 2020). "Secondary hyperparathyroidism is associated with renal osteodystrophy with increased bone turnover, while deficient PTH levels are associated with adynamic bone disease." (PMID 32823917, 2020). "Vitamin D is an important inhibitor of PTH synthesis in the parathyroid and its deficiency is associated with elevated blood PTH concentrations, defined as secondary hyperparathyroidism." (PMID 32813765, 2020). "Decreased bone mineral density in patients with secondary hyperparathyroidism is mainly caused by high bone turnover secondary to high levels of circulating PTH." (PMID 31573378, 2019). "The association between PTH and UA is further supported by the use of cinacalcet in secondary hyperparathyroidism (SHPT)." (PMID 31491937, 2019). "A hallmark of CKD is secondary hyperparathyroidism, characterized by an increased production and release of PTH, reduced expression of calcium‐sensing and vitamin D receptors on the surface of parathyroid cells, and hyperplasia and hypertrophy of these cells." (PMID 30927339, 2019). "Secondary hyperparathyroidism and altered levels of parathyroid hormone (PTH) are associated with vascular events in chronic kidney disease." (PMID 29478201, 2018). "Elevated expression of PTH (secondary hyperparathyroidism) caused by poor calcium and vitamin D uptake can generate skeletal calcium mobilization to the blood stream in order to stabilize the levels of calcium intestinal absorption, favoring bone resorption." (PMID 29651097, 2018). "PTH disturbances and secondary hyperparathyroidism can cause radiolucent jaw lesions referred to as “Brown Tumors”." (PMID 30225253, 2018). "Secondary hyperparathyroidism was defined as elevated serum PTH level associated with serum 25(OH) level lower than 30 ng/mL and/or serum calcium level lower than 8.5 mg/dL." (PMID 29445220, 2018).
secondary hyperparathyroidism (continued). "The PTH also stimulates the renal synthesis of 1,25-dihydroxyvitamin D. The deficiency of vitamin D produces secondary hyperparathyroidism." (PMID 30581552, 2018). "Low serum 25-OH-D is usually associated with high circulating PTH level, a condition known as secondary hyperparathyroidism." (PMID 30200421, 2018). "The consequence is an increased synthesis and secretion of parathyroid hormone (secondary hyperparathyroidism) causing to the low levels of calcium." (PMID 28210437, 2017). "During the course of CKD, 1,25-(OH)2D3 deficiency, calcium phosphorus metabolism disorders, secondary hyperparathyroidism and serum calcium concentration decreases further stimulate parathyroid secretion of more PTH." (PMID 28741985, 2017). "Multiple studies have shown that PTH was predictive for vascular disease and death associated with disorders of mineral metabolism including primary and secondary hyperparathyroidism and CRF." (PMID 28115793, 2017). "Increased PTH concentration was also correlated with enhanced fatty acid oxidation in the myocardium in animals with secondary hyperparathyroidism caused by chronic renal failure." (PMID 28596785, 2017). "For instance, severe secondary hyperparathyroidism, caused by the elevation of circulating parathyroid hormone (PTH), is associated with the incidence of fractures in CKD patients undergoing dialysis treatment." (PMID 25874620, 2015). "Conversely, in dialysis patients with secondary hyperparathyroidism, heavy smoking was independently associated with high PTH levels." (PMID 25514572, 2014). "Although a significant inverse association between PTH and 25OHD was seen in our morbidly obese adolescent population, only a small percentage of patients (3.7%) had clear evidence of secondary hyperparathyroidism." (PMID 23724340, 2013). "A study of PTH response in elderly with hypovitaminosis D showed that the simultaneous presence of secondary hyperparathyroidism was associated with increased bone turnover and fracture risk, as well as shorter survival." (PMID 24073266, 2013). "Numerous experiments have shown that a rise in PTH can be caused by other factors, such as primary hyperparathyroidism and secondary hyperparathyroidism." (PMID 23537001, 2013). "In animal models continuous infusion of PTH (cPTH) mimics primary and secondary hyperparathyroidism leading to osteoclastic bone resorption and bone loss." (PMID 24278766, 2013). "Many factors have been proposed as the reasons; however, the persistence of secondary hyperparathyroidism, associated with a change in the set-point of Ca-controlled PTH secretion, is considered the most important factor." (PMID 25013642, 2012). "Secondary hyperparathyroidism is often associated with osteomalacia; we thus measured serum levels of PTH." (PMID 22629419, 2012). "Excess PTH, as is seen in primary and secondary hyperparathyroidism, is associated with increased mortality, and high PTH levels have been related to fatal events in the general population." (PMID 22590632, 2012). "Secondary hyperparathyroidism, where continuous PTH secretion does occur, is also associated with increased osteoblast activity and increased bone matrix production." (PMID 21829585, 2011). "Because secondary hyperparathyroidism is associated with morbidity and mortality in patients with chronic kidney disease, suppression of parathyroid hormone (PTH) and minimization of associated derangements in mineral metabolism are cardinal therapeutic goals." (PMID 21876786, 2011). "PTH dysregulation may be an overlooked cause of bone mineral loss, neuromuscular symptoms, and secondary hyperparathyroidism in PLWHIV." (PMID 41295288, 2025). "Similarly, the parathyroid function index (PF index = Ca × PTH/P) showed 94.6% specificity in distinguishing normocalcemic PHPT from secondary hyperparathyroidism due to vitamin D deficiency." (PMID 41210508, 2025).
secondary hyperparathyroidism (continued). "Also, CAS has been linked to higher levels of parathyroid hormone (PTH) in patients with secondary hyperparathyroidism and renal insufficiency, paving the way for studies evaluating vitamin D supplementation in these patients to prevent CAS progression." (PMID 39941574, 2025). "Despite the knowledge that low vitamin D causes secondary hyperparathyroidism and that PTH exerts direct stimulatory actions on many cells and tissues, to the best of our knowledge, PTH has not been directly studied in the context of outcome in childhood malignancies." (PMID 39141058, 2024). "In addition, DKD patients can indirectly stimulate parathyroid hormone secretion, causing secondary hyperparathyroidism, which leads to increased osteoclast activity and decreased bone mineralization, further exacerbating the bone conversion imbalance." (PMID 39687075, 2024). "Increased PTH concentration might reflect secondary hyperparathyroidism caused by low levels of vitamin D and calcitriol." (PMID 38542041, 2024). "Finally, the occurrence of low serum ionized calcium is linked to secondary hyperparathyroidism and inceased secretion of parathyroid hormone (PTH)." (PMID 38609861, 2024). "Additionally, high PTH levels, which are linked to secondary hyperparathyroidism in ESRD patients, have been reported in other studies to correlate with cancer risk through mechanisms involving bone turnover and chronic inflammatory processes." (PMID 39712803, 2024). "From another perspective, therapies that lower PTH levels to the recommended range have been linked to improved bone properties and fewer fractures in patients with secondary hyperparathyroidism, indicating that elevated PTH levels are detrimental to bone health in dialysis patients." (PMID 39188768, 2024). "Furthermore, secondary hyperparathyroidism induced by VitD deficiency and the accompanying increase in PTH levels can diminish the efficacy of bisphosphonates." (PMID 39640483, 2024). "Additionally, this patient has a history of CKD stage 3, a well-known cause of secondary hyperparathyroidism, which is characterized by elevated PTH, low calcium, and high phosphorus." (PMID 39355148, 2024). "However, placing the PTH assay among the PA panel of investigations seems a logical step based on the mentioned studies; identifying the subgroup with secondary hyperparathyroidism helps the cardio-metabolic risk assessment as well." (PMID 38139166, 2023). "Furthermore, it is necessary to exclude renal calcium loss as an additional drive of increased PTH secretion (as a form of secondary hyperparathyroidism)." (PMID 37251673, 2023). "PTH is a major hormone in charge of bone resorption, and its serum levels may be a useful identification risk marker of secondary hyperparathyroidism and metabolic bone disease in extremely low birth weight neonates." (PMID 36639750, 2023). "Moreover, chronic uremia causes low levels of plasma calcium and high phosphate levels that increase the synthesis and secretion of parathyroid hormone, causing secondary hyperparathyroidism." (PMID 36316853, 2022). "Furthermore, some observational studies in cases of secondary hyperparathyroidism have demonstrated the association of PTH with renal anemia or immunodeficiency." (PMID 35710357, 2022). "Other factors that have been shown to affect bone homeostasis in NF1 are the elevated renal excretion of calcium, reduced levels of total and ionized plasma calcium and magnesium levels, and increased circulating levels of parathormone (PTH) that were associated with secondary hyperparathyroidism." (PMID 35054138, 2022). "Renal hyperparathyroidism is a common complication of chronic kidney disease and renal failure that can be further classified into secondary hyperparathyroidism or tertiary hyperparathyroidism according to the serum calcium level and the underlying mechanism of elevated parathyroid hormone (PTH)." (PMID 33477403, 2021).
secondary hyperparathyroidism (continued). "Most of the previous studies focused on the association of PTH and mineral bone disease; however, few studies have mentioned that secondary hyperparathyroidism may contribute to the cardiovascular complications of CKD." (PMID 33691727, 2021). "Moreover, increased renal calcium excretion is a well-known cause of secondary hyperparathyroidism, where PTH induced bone demineralization by increasing bone resorption." (PMID 34977081, 2021). "PTH then acts on bone to release calcium, which inadvertently increases also Pi release leading to a vicious cycle with continuous bone loss and extraskeletal calcifications with secondary hyperparathyroidism." (PMID 33416083, 2021). "PTH is high in deficient serum 25(OH)D, characterizing secondary hyperparathyroidism, which is associated with a reduction in strength that could compromise functioning." (PMID 32937653, 2020). "Lower serum albumin levels and worsening secondary hyperparathyroidism were also associated with greater likelihood of gout [OR 1.09 (1.03–1.14) per 1 g/dL decrease in albumin, and OR 1.33 (1.14–1.56) per 50 pg/mL increase in PTH, all p <0.005." (PMID 30682034, 2019). "To address this issue, we analyzed PTH levels prospectively determined at the time of transplantation and at three month post-transplantation and identified a significant association between secondary hyperparathyroidism and AVN." (PMID 30794689, 2019). "The trial titled “Evaluation of Cinacalcet Hydrochloride Therapy to Lower Cardiovascular Events (EVOLVE)” showed a non-significant 7% reduction in the risk of death with the use of cinacalcet to lower PTH level in patients with moderate to severe secondary hyperparathyroidism." (PMID 31107896, 2019). "This pro-hypertrophic effect of PTH may support the association between LV mass and PTH in ESRD patients with secondary hyperparathyroidism." (PMID 30200452, 2018). "High levels of PTH have been linked with increased arterial calcification in a population-based study in Sweden and it is well known that secondary hyperparathyroidism is an indicator of poor outcome in renal diseases in which activation of vitamin D is deficient." (PMID 26078787, 2015). "Further studies are needed to determine whether PTH affects lung tissue or lung disease causes secondary hyperparathyroidism." (PMID 26398210, 2015). "Common complications in CKD include secondary hyperparathyroidism, characterized by high-turnover renal osteodystrophy, with increased bone turnover leading to bone fragility and an increased risk of fractures, involving disturbances in calcium, phosphorus, PTH, vitamin D, and FGF23 levels." (PMID 40447997, 2025). "Additionally, the notable decrease in PTH observed in denosumab treatment group might also be associated with the correction of secondary hyperparathyroidism." (PMID 38181430, 2024). "Kidney function is mandatory to be evaluated in order to exclude secondary hyperparathyroidism in chronic kidney disease (stages higher than G3 that correspond to a glomerular filtration rate of <60 mL/min/1.73 m2 are usually associated with a secondary increase in PTH." (PMID 39518465, 2024). "It is known that persistent secondary hyperparathyroidism, such as that induced by idiopathic hypercalciuria or malabsorption-related vitamin D deficiency, may stimulate parathyroid cell proliferation and autonomous PTH hypersecretion." (PMID 37065733, 2023). "While day 1 PTH has a sensitivity of 83.4% and a specificity of 100% for predicting postoperative hypoparathyroidism, its utility may be limited in vitamin D-deficient patients who have secondary hyperparathyroidism." (PMID 33498810, 2021). "Therefore in the same individual, the coexistence of increased plasma PTH associated with values of serum 25(OH)D and eGFR above, and 24-h urinary calcium below the relative cut-offs, might be compatible with a form secondary hyperparathyroidism." (PMID 31176307, 2019).